EVC (EvC ciliary complex subunit 1)
Description:
Component of the EvC complex that positively regulates ciliary Hedgehog (Hh) signaling. Involved in endochondral growth and skeletal development.
Synonyms: DWF-1; EVC1; EVCL
Tractability: Antibody: UniProt places it where antibodies can reach, with medium confidence; UniProt predicts a signal peptide or a membrane-spanning region; its Gene Ontology location is reachable by antibodies, with medium confidence. PROTAC: ubiquitination databases record sites on it.
Gene: Protein-coding gene on chromosome 4 (5,711,201 to 5,814,305, forward strand). Ensembl gene ENSG00000072840.
Subcellular location: Cell membrane; Cytoplasm, cytoskeleton, cilium basal body; Cell projection, cilium; Cell projection, cilium membrane
Subcellular location (Human Protein Atlas): Basal body; Nucleoplasm; Cytosol; Primary cilium
Pathways (Reactome):
Signal Transduction: Activation of SMO; Hedgehog 'on' state
Gene Ontology:
Biological process: endochondral bone growth; muscle organ development; positive regulation of smoothened signaling pathway; skeletal system development; cartilage development; smoothened signaling pathway
Cellular component: cilium; ciliary basal body; ciliary membrane; plasma membrane; plasma membrane protein complex
Genetic constraint (gnomAD): Loss-of-function variants: 111 observed, 114.58 expected, observed/expected ratio (o/e) 0.97, 90% interval 0.83 to 1.13. The upper end of that interval is the gene's LOEUF score, 1.13, which puts it in group 4 of 6, group 1 being the genes least tolerant of losing a copy. Missense variants: 1,349 observed, 1,201.2 expected, observed/expected ratio (o/e) 1.12, 90% interval 1.07 to 1.17. Synonymous variants: 597 observed, 514.69 expected, observed/expected ratio (o/e) 1.16, 90% interval 1.08 to 1.24.
Gene-disease validity (ClinGen):
ClinGen rates the evidence that EVC causes each of these diseases.
Ellis-van Creveld syndrome (autosomal recessive): Definitive. Ellis-van Creveld syndrome (EVC) is a skeletal and ectoderlam dysplasia characterized by a tetrad of short stature, postaxial polydactyly, ectodermal dysplasia, and congenital heart defects.
Homologues: Orthologues: chimpanzee EVC (98% identical), macaque EVC (95% identical), dog EVC (82% identical), pig EVC (78% identical), guinea pig EVC (70% identical), mouse Evc (68% identical), rat Evc (68% identical), tropical clawed frog evc (41% identical). Paralogues in human: EVC2 (16% identical).
Diseases named in the same sentence as EVC in open-access papers:
EVC is named in the same sentence as 36 diseases in open-access papers, as found by Europe PMC text mining. Sharing a sentence is not in itself a finding about the gene and the disease. The quoted sentences say what the papers report.
Ellis-van Creveld syndrome (11 papers, 2007 to 2024). "In addition other genes enriched included EVC: Ellis-van Creveld syndrome (EvC) and Weyers acrodental dysostosis which is linked to hedgehog pathway and is therefore related to Wnt signaling pathway involved in many cancers." (PMID 31511569, 2019). "For instance, mutations in EVC and DHCR7 result in heart defects in humans (Ellis van Creveld Syndrome, OMIM 225500, Smith-Lemli-Opitz syndrome OMIM 270400) but not in the mouse." (PMID 23082118, 2012). "In addition, the EvC ciliary complex subunit 1 (EVC1) and subunit 2 (EVC2) genes were found to be causative for the formation of the Ellis-van Creveld syndrome manifested also by maxillary hypoplasia and mandibular prognathism." (PMID 37441579, 2023). "Among the positional candidate genes, EVC and EVC2, near SNPs associated with HD on CFA03, cause Ellis–van Creveld syndrome (EVC, MIM 225500), a rare autosomal recessive chondrodysplasia also called chondroectodermal or mesoectodermal dysplasia." (PMID 20949002, 2010).
Marfan syndrome (2 papers, 2014 to 2017). A disorder of the connective tissue. "All these genes are highly expressed in cartilage and mutations in these genes can cause chondrodysplasia (EVC, EVC2), Marfan syndrome (MFAP1) or restless legs syndrome (PTPRD)." (PMID 24802516, 2014).
adult T cell leukemia (1 paper, 2021). "Indeed, in adult T cell leukemia (ATL), the HTLV-1 TAX transcription factor epigenetically upregulates Ellis Van Creveld (EVC) family members, EVC1 and EVC2, both of which have been associated with the cellular HH activity and thus provides the pro-survival attributes of ATL cells." (PMID 34422814, 2021).
atrial septal defect (1 paper, 2025). Interauricular communication is a congenital malformation characterized by a communication between the atrial chambers of the heart. "Variants in genes associated with atrial septal defects and ventricular septal defects (e.g., DOCK6, EOGT, EP300, EVC, EVC2, and SEMA3C) have also been identified in patients." (PMID 41153298, 2025).
ciliopathy (1 paper, 2016). A genetic disorder of the cellular cilia or the cilia anchoring structures, the basal bodies, or of ciliary function. "EvC syndrome is also categorized as a ciliopathy because of ciliary localization of proteins encoded by the two causative genes, EVC and EVC2 (aka LIMBIN)." (PMID 28027321, 2016).
Cleidocranial dysplasia (1 paper, 2018). "Various genes (RUNX2, PLOD, EVC, GLA, APC, NEMO) have been associated with supernumerary teeth formation in several syndromes, such as Cleidocranial dysplasia, Ehlers-Danlos Type IV, Ellis-Van Creveld, Fabry disease, Familial adenomatous polyposis, and Incontinentia pigmenti." (PMID 30148467, 2018).
dwarfism (1 paper, 2016). "The defective Hedgehog signaling in chondrocytes is therefore the speculated reason for dwarfism in EvC patients." (PMID 28027321, 2016). "Our findings explain differences between proposed functions of EVC/EVC2 based on biochemical approaches and symptoms found in the EvC patients, and thus provide insight for better options to treat dwarfism found in EvC patients." (PMID 28027321, 2016).
hypospadias (1 paper, 2019). Hypospadias is the displacement of the urethral meatus on the ventrum of the penis. "Patient 7 presented five variants in five genes: EVC, MAML3, NOTCH2, PPARGC1B and WDR11; four of them associated with hypospadias or male gonadal development and one, MAML3, with female gonadal development." (PMID 31555317, 2019).
microtia (1 paper, 2014). "The EVC gene was selected for its roles in cartilage development, and the NKX3-2 and HMX1 gene was for their link to syndromic microtia." (PMID 24983964, 2014). "Based on the knowledge that microtia is one of the facial deformities with cartilage abnormity, we suggest detailed investigations on the EVC, EVC2, SLC2A9, NKX3-2 and HMX1 genes for this isolated microtia pedigree." (PMID 24983964, 2014).
Verma-Naumoff syndrome (1 paper, 2007). "EVC belongs to the short rib-polydactyly group (SRP) and these SRPs, especially type III (Verma-Naumoff syndrome), are discussed in the prenatal differential diagnosis." (PMID 17547743, 2007).
skeletal dysplasia (3 papers, 2010 to 2026). Any Mendelian diseases that affects growth and development of the skeleton. "EVC is a causal gene of EvC syndrome, a rare, recessive congenital skeletal dysplasia characterized by short ribs, short limbs, polydactyly, and dystrophic hair and teeth." (PMID 41550739, 2026). "Ellis–van Creveld (EvC) syndrome, caused by variants in the EVC gene, is a rare genetic skeletal dysplasia." (PMID 37157924, 2023). "Ellis–van Creveld (EvC) syndrome, caused by variants in EVC, is a rare genetic skeletal dysplasia." (PMID 37157924, 2023). "As the mutations in these genes always cause skeletal dysplasia, we suggest that some novel mutations in EVC2 and EVC may be relevant to the form of mandibular prognathism." (PMID 20844756, 2010).
cancer (2 papers, 2019 to 2025). A tumor composed of atypical neoplastic, often pleomorphic cells that invade other tissues. "These modules contained several cancer regulators such as Intraflagellar Transport (IFT) complex proteins (IFT74, IFT88), BBSome complex proteins (BBS2, BBS7, BBS9, BBS12), exocyst complex components (EXOC3, EXOC4, EXOC6B, EXOC7, and EXOC8), TTC8, TTC21B, EVC, and NEK1." (PMID 40700427, 2025).
EVC also shares sentences with these, for which no sentence is quoted: acrofacial dysostosis (1 paper); autism (1); chondrodysplasia (1); cleft palate (1); Cornelia de Lange syndrome 4 (1); cryptorchidism (1); Fabry disease (1); Familial adenomatous polyposis (1); gastric tumors (1); incontinentia pigmenti (1); microdeletion syndrome (1); Microdontia (1); Micropenis (1); Oligodontia (1); Opitz G/BBB syndrome (1); pneumonia (1); poliomyelitis (1); restless legs syndrome (1); rheumatoid arthritis (1); Smith-Lemli-Opitz syndrome (1); ventricular septal defect (1); Weyers acrofacial dysostosis (1); Williams-Beuren syndrome (1); Wolf-Hirschhorn syndrome (1).